BMP2K (BMP2 inducible kinase)
Description:
May be involved in osteoblast differentiation.
Synonyms: BIKe; HRIHFB2017; DKFZp434K0614
Tractability: Small molecule: a structure with a bound ligand is known; a high-quality ligand is known; it belongs to a druggable protein family. PROTAC: it is named in the literature on targeted protein degradation; ubiquitination databases record sites on it; its protein half-life has been measured; a small molecule that binds it is known.
Target class: Protein Kinase; Other protein kinase NAK family; Other protein kinase group; Enzyme; Kinase
Chemical probes: SGC-AAK1-1 (high quality), SGC-CDKL2/AAK1/BMP2K-1 (high quality)
Gene: Protein-coding gene on chromosome 4 (78,776,342 to 78,916,365, forward strand). Ensembl gene ENSG00000138756.
Subcellular location: Nucleus
Subcellular location (Human Protein Atlas): Nuclear speckles
Gene Ontology:
Molecular function: protein binding; protein serine kinase activity; AP-2 adaptor complex binding; phosphatase regulator activity; protein serine/threonine kinase activity; ATP binding; protein kinase activity
Biological process: positive regulation of Notch signaling pathway; regulation of bone mineralization; regulation of clathrin-dependent endocytosis
Cellular component: nuclear speck; nucleus
Genetic constraint (gnomAD): Loss-of-function variants: 52 observed, 85.34 expected, observed/expected ratio (o/e) 0.61, 90% interval 0.49 to 0.77. The upper end of that interval is the gene's LOEUF score, 0.77, which puts it in group 3 of 6, group 1 being the genes least tolerant of losing a copy. Missense variants: 1,201 observed, 1,244.4 expected, observed/expected ratio (o/e) 0.97, 90% interval 0.92 to 1.01. Synonymous variants: 438 observed, 447.65 expected, observed/expected ratio (o/e) 0.98, 90% interval 0.9 to 1.06.
Homologues: Orthologues: chimpanzee BMP2K (99% identical), macaque BMP2K (97% identical), dog BMP2K (88% identical), rabbit BMP2K (87% identical), mouse Bmp2k (82% identical), rat Bmp2k (81% identical), guinea pig BMP2K (80% identical), pig BMP2K (79% identical), tropical clawed frog bmp2k (64% identical), zebrafish bmp2k (34% identical). Paralogues in human: AAK1 (33% identical), STK16 (8% identical).
Diseases named in the same sentence as BMP2K in open-access papers:
BMP2K is named in the same sentence as 34 diseases in open-access papers, as found by Europe PMC text mining. Sharing a sentence is not in itself a finding about the gene and the disease. The quoted sentences say what the papers report.
myopia (3 papers, 2011 to 2022). "In a separate pathological setting, a BMP2K variant, was reported to be strongly correlated with the development of high myopia." (PMID 23029096, 2012). "Another study also reported that variations in the BMP2K gene are strongly correlated with high myopia in the Taiwanese population." (PMID 21403850, 2011).
breast carcinoma (1 paper, 2012). "To further strengthen the in vivo relevance of our data, we determined the expression of Peg3 and Bmp2k in the same orthotopic mammary tumor xenografts as used above." (PMID 23029096, 2012). "Importantly, we demonstrate a reproducible induction of a presumed tumor suppressor gene (Peg3) within the stromal compartment as well as implicating a novel role for Bmp2k in breast cancer samples." (PMID 23029096, 2012). "No data were available in the ONCOMINE for either BMP2K or ZC3HAV1 related to breast cancer." (PMID 23029096, 2012).
Chronic Lymphocytic Leukemia (1 paper, 2020). "BMP2K was previously suggested to confer resistance to fludarabine in Chronic Lymphocytic Leukemia." (PMID 32322386, 2020). "BMP2K may confer resistance to fludarabine in Chronic Lymphocytic Leukemia (CLL)." (PMID 32322386, 2020).
colon cancer (1 paper, 2020). "FuSiOn identified ten kinases (BMP2K, DCLK3, LIMK2, MAP2K5/MEK5, MAP3K3/MEKK3, ROS1, SIK2, TAOK2, ULK1, and ULK2) whose depletion mimicked the phenotypic effect of p62 depletion in HCT116 colon cancer cells." (PMID 33101709, 2020).
developmental dysplasia of the hip (1 paper, 2021). A spectrum of hip abnormalities commonly presenting in infancy involving the relationship between the femoral head and the acetabulum and that includes subluxation or dislocation at rest or upon provocation. "Interestingly, BMP2K was mutated in the IDR in developmental dysplasia of the hip (DDH) and high myopia diseases, suggesting functional roles of LLPS in BMP2K regulation and functions." (PMID 33988507, 2021).
gastritis (1 paper, 2023). Inflammation of the stomach. "In this study, we screened 11 important lncRNAs (AFAP1-AS1, MIR155HG, LINC00472, and FAM201A) and mRNAs (CASP10, SLC26A2, TRIB1, BMP2K, SCAMP1, TNKS1BP1, and MBOAT2) according to the gene expression profiles of gastric epithelial tissues in different stages of Hp infection-induced gastritis." (PMID 37249580, 2023).
leukemia (1 paper, 2020). A malignant (clonal) hematologic disorder, involving hematopoietic stem cells and characterized by the presence of primitive or atypical myeloid or lymphoid cells in the bone marrow and the blood. "BMP2K upregulation was observed in human megakaryopoiesis and leukemia cells whereas BMP2K was downregulated in AMKL cells forced to undergo terminal differentiation." (PMID 32322386, 2020).
parathyroid adenomas (1 paper, 2019). "Among those genes up-regulated in parathyroid adenomas, some, such as MED12, KMT5A, BMP2K, and ATAD2, are implicated in cell proliferation and transcriptional regulation, supporting the notion that they potentially contribute to tumorigenesis." (PMID 30832348, 2019).
tumor (15 papers, 2012 to 2025). "Systemic treatment with decorin resulted in an induction of Peg3 as well as Bmp2k and Zc3hav1 within the tumor stroma as visualized via immunofluorescence and quantified using three-dimensional surface plots of the fluorescent signal." (PMID 23029096, 2012). "Analysis of these stromal genes in context of the co-culture via qPCR revealed a recapitulation of the expression patterns of Peg3, Bmp2k, and Zc3hav1 (P<0.001), the same stromal genes verified as induced by decorin within the tumor xenografts." (PMID 23029096, 2012). "Thus, these in vivo data provides further proof that decorin significantly affects the tumor microenvironment via induction of Peg3, Bmp2k and Zc3hav1 at the protein and transcriptional levels as suggested by the mixed microarray data." (PMID 23029096, 2012).
cancer (9 papers, 2012 to 2025). A tumor composed of atypical neoplastic, often pleomorphic cells that invade other tissues. "Predicted HFI SNVs were not distributed evenly across disease subsets; SNVs in ULK4, BMP2K, PALB2, ALPK3 were more frequent in triple negative cancers (TNBC) whereas SNVs in EPHA2 was more common in ER positive cancers." (PMID 26420498, 2015).
infection (2 papers, 2023 to 2024). The state of being infected such as from the introduction of a foreign agent such as serum, vaccine, antigenic substance or organism. "Moreover, numerous Ser/Thr kinases (STKs) were either increased (e.g., GRK2, ROCK2, ROCK1, PAK1) or decreased (e.g., BMP2K, TNIK, MYLK, and NRBP1) in expression in the patient samples, suggesting a widespread change in the kinome caused by pathogen infection." (PMID 38389037, 2024).
blood cancer (1 paper, 2020). "We found that K562 human erythroleukemia cells contain much higher amounts of BMP2K than various immortalized, solid tumor or non-erythroid blood cancer cell lines." (PMID 32795391, 2020).
BMP2K also shares sentences with these, for which no sentence is quoted: acute myeloid leukemia (2 papers); glioma (2); osteoporosis (2); pancreatic cancer (2); acute megakaryoblastic leukemia (1); autoimmune disease (1); cardiovascular disease (1); colorectal cancer (1); COVID-19 (1); dengue virus infection (1); eosinophilia (1); glioblastoma (1); hematological cancers (1); hyperopia (1); lymphoid neoplasm (1); male infertility (1); measles (1); myelodysplastic syndrome (1); myeloid neoplasm (1); Obesity (1); T cell lymphoma (1); viral infections (1).